CYP2C8 (cytochrome P450 family 2 subfamily C member 8)
Diseases named in the same sentence as CYP2C8 in open-access papers (continued):
Sharing a sentence is not in itself a finding about the gene and the disease.
liver fibrosis (2 papers, 2012 to 2021). "Carriers of the CYP2C8*3 allele have faster metabolism rate of pioglitazone and have less improvement in liver fibrosis after pioglitazone intervention (p = 0.026)." (PMID 33397443, 2021).
lupus (2 papers, 2023 to 2025). "Additionally, studies on genetic polymorphisms of CYP2A6 and CYP2C8 in the context of CYC metabolism are limited, particularly in patients with systemic lupus erythematosus (SLE)." (PMID 40630120, 2025).
Plasmodium falciparum malaria (2 papers, 2012 to 2021). Malaria resulting from infection by Plasmodium falciparum. "This study aimed to assess the influence of these CYP2C8 polymorphisms on the efficacy and tolerability of artesunate–amodiaquine (AS–AQ) treatment for uncomplicated Plasmodium falciparum malaria in Zanzibar." (PMID 33588856, 2021). "The aim of this study was to investigate cytochrome P450 2C8*2 (CYP2C8*2) distribution and allele frequency in three populations from West and East Africa exposed to Plasmodium falciparum malaria." (PMID 22531455, 2012).
acute monocytic leukemia (1 paper, 2011). Acute monoblastic leukemia (AML-M5), is one of the most common subtypes of acute myeloid leukemia (AML) that is either comprised of more than 80% of monoblasts (AML-M5a) or 30-80% monoblasts with (pro)monocytic differentiation (AML-M5b). "Although we found CYP2J2 and CYP2C8 mRNA in human total leukocytes, lymphocyte and monocyte fractions (but not PMNs), the levels of mRNA were consistently lower than those found in our THP-1 cells (a human acute monocytic leukemia cell line)." (PMID 22028915, 2011).
adenoma (1 paper, 2005). A neoplasm arising from the epithelium. "In contrast, mean protein level of CYP2C8 was significantly lower in unaffected, macroscopically normal colon mucosa obtained from patients with adenoma than in samples obtained from disease-free controls." (PMID 16281975, 2005). "Specifically, protein concentration of CYP2C8 in colon mucosa obtained from patients with adenoma was ~85% lower than in tissue obtained from disease-free controls." (PMID 16281975, 2005). "At the level of protein, CYP2C8, CYP3A4, and CYP3A5 protein concentration was found to be significantly lower in normal tissue of patients with adenoma than in colon mucosa of disease-free controls." (PMID 16281975, 2005). "However, in normal tissue of patients with adenomas, protein levels of CYP2C8, CYP3A4 and CYP3A5, but not that of CYP2E1, were significantly lower than in biopsies obtained from disease-free controls." (PMID 16281975, 2005).
atherosclerosis (1 paper, 2014). A disease characterized by the build-up of fatty material and calcium deposition in the arterial wall resulting in partial or complete occlusion of the arterial lumen. "The formation and area of atherosclerosis plaque was decreased significantly in teh aortic artery in the CYP2C8 gene overexpression group." (PMID 25017038, 2014). "Our previous study indicated that CYP2C8 exerted a protective effect on atherosclerosis induced by a western-type diet in APOEKO+/−CYP2C8Tg+/− and CYP2C8Tg+/− mice." (PMID 25017038, 2014). "Thus, we revealed that CYP2C8-derived EETs prevented the early pathogenesis of atherosclerosis by modulating vascular inflammation and ROS." (PMID 25017038, 2014). "However, how CYP2C8-derived EETs affect ROS signaling pathways that lead to inflammation and atherosclerosis remains to be determined." (PMID 25017038, 2014). "As previous studies have demonstrated that the migration of VSMCs was associated with the formation of atherosclerosis, the decrease of the migration of VSMCs by CYP2C8-derived EETs may contribute to the improvement of atherosclerosis." (PMID 25017038, 2014).
Azoospermia (1 paper, 2024). Absence of any measurable level of sperm,whereby spermatozoa cannot be observed even after centrifugation of the semen pellet. "An SNP associated with azoospermia and severe oligozoospermia was also identified in an intronic region of the CYP2C8 gene." (PMID 39057031, 2024).
cholestasis (1 paper, 2015). Impairment of the bile flow caused by obstruction within the liver, or outside the liver in the bile duct system. "Association of CYP2C8 with deregulated bile acid homeostasis and drug induced cholestasis have been reported before." (PMID 26582990, 2015). "We identified cholestasis and increased bilirubin and GGT levels as factors being significantly associated with at least one microsomal CYP2C8 phenotype." (PMID 26582990, 2015). "In particular for diclofenac-induced cholestasis, it was suggested that allelic variants in UGT2B7, CYP2C8, and MRP2 may cause an increase in the level of reactive metabolites leading to protein-diclofenac adducts that then produce toxicity." (PMID 26582990, 2015).
colonic adenoma (1 paper, 2005). "However, in the present study protein levels of CYP2C8, CYP3A4, and CYP3A5 were found to be significantly lower in normal unaffected colonic mucosa of patients with colonic adenoma in comparison with disease-free controls." (PMID 16281975, 2005).
gastric cancer (1 paper, 2021). A primary or metastatic malignant neoplasm involving the stomach. "A phase 1 study of 6 Japanese patients with advanced/recurrent gastric cancer (JapicCTI‐142420) found that the PK and safety profiles of napabucasin were not affected by paclitaxel, a CYP2C8 and CYP3A4 substrate." (PMID 34107166, 2021).
gynecological cancer (1 paper, 2025). "Meta-analyses and large patient cohorts, primarily involving breast or gynecological cancer patients treated with paclitaxel or docetaxel, indicate an increased risk of chemotherapy-induced peripheral neuropathy (CIPN) associated with CYP2C8, particularly of grade ≥2 or ≥3 severity." (PMID 41300713, 2025).
Hypertension (1 paper, 2023). The presence of chronic increased pressure in the systemic arterial system. "Combination of genotypes CYP2C8 rs7909236 TT and CYP2C19 rs4244285 GG was associated with increased hypertension risk in a Russian population." (PMID 37024851, 2023).
injury (1 paper, 2022). Damage inflicted on the body as the direct or indirect result of an external force, with or without disruption of structural continuity. "Moreover, we found that SNPs in CYP2C8 and CYP2C9 could be a potential risk factor for both macitentan- and selexipag-induced liver injury, thus providing a possible marker for early identification of subjects with high risk of developing hepatotoxicity." (PMID 36258237, 2022).
insomnia (1 paper, 2025). A sleep disorder characterized by difficulty in falling asleep and/or remaining asleep. "The increase in chloroquine levels associated with the CYP2C8*2 variant can potentially impact its tolerability, similar to what has been observed with amodiaquine in children from Zanzibar, where the CYP2C82 variant led to higher rates of dizziness and insomnia." (PMID 40238288, 2025).
ischemic heart disease (1 paper, 2022). "In explanted left ventricular tissue from humans with ischemic heart disease, CYP2J2 and CYP2C8 levels were lower in the infarcted regions." (PMID 35665247, 2022).
kidney damage (1 paper, 2019). "The results showed that CYP2C8*3 variant was significantly associated with kidney damage when controlling for meaningful covariates [OR = 3.35 (1.03–10.93), p = 0.045]." (PMID 31622444, 2019).
leukemia (1 paper, 2022). A malignant (clonal) hematologic disorder, involving hematopoietic stem cells and characterized by the presence of primitive or atypical myeloid or lymphoid cells in the bone marrow and the blood. "It has been reported that CYP2C8 polymorphisms can significantly change the imatinib metabolism in patients with leukemia through both gain- and loss-of-function mechanism." (PMID 36246885, 2022).
liver cancer (1 paper, 2024). An epithelial or non-epithelial malignant neoplasm that arises from the liver. "The results showed that UBE2C, PTTG1, TOP2A and SPP1 were positive, FCN3, SLC22A1, ADH4, CYP2C8, SLC10A1, and FBP1 were negative in liver cancer tissues." (PMID 38664521, 2024).
lung adenocarcinoma (1 paper, 2023). A carcinoma that arises from the lung and is characterized by the presence of malignant glandular epithelial cells. "Furthermore, the paclitaxel resistance of A549 cells (human lung adenocarcinoma cell line) has been reported to be associated with the PXR-mediated transcriptional induction of CYP2C8 enzyme and Pgp transporter protein (ABCB1 transporter)." (PMID 37686184, 2023). "In the treatment naïve lung adenocarcinoma samples, the multiplication of paclitaxel-metabolizing CYP2C8 and/or CYP3A4 was detected, and the CYP copy number increase was more prevalent in non-responder patients than in responders to paclitaxel therapy." (PMID 37686184, 2023). "For the estimation of patients’ paclitaxel-metabolizing capacity, CYP2C8, CYP3A4 and CYP3A5 alleles (CYP2C8*3, CYP2C8*4, CYP3A4*1B, CYP3A4*22, CYP3A5*3) most common in Caucasian populations were identified in lung adenocarcinoma patients on paclitaxel therapy (N = 17)." (PMID 37686184, 2023). "A sensitive qPCR-based method with an optimal normalization procedure was presented here for the assessment of the copy numbers of paclitaxel-metabolizing CYP2C8 and CYP3A4 in lung adenocarcinoma samples." (PMID 37686184, 2023). "Alterations in copy numbers of paclitaxel-metabolizing CYPs (CYP2C8, CYP3A4) were aimed to be determined in primary lung adenocarcinoma samples prior to therapy." (PMID 37686184, 2023). "In the present study, the copy number alterations of two drug-metabolizing CYP genes, CYP2C8 and CYP3A4, were determined in lung adenocarcinoma samples using normal lung tissues or blood samples for normalization." (PMID 37686184, 2023). "The copy numbers of both the target (CYP2C8, CYP3A4) and the reference genes (ALB, B2M, BCKDHA, F5, CD36, MPO, TBP, RPPH1) established in primary lung adenocarcinoma by the qPCR-based method were congruent with those determined by next-generation sequencing (for 10 genes, slope = 0.9498, r2 = 0.72)." (PMID 37686184, 2023). "For the paclitaxel-metabolizing CYPs, deletion of CYP2C8, but not of CYP3A4 was detected in primary lung tumour and in lung and liver metastases (the average copy number of CYP2C8 in primary lung adenocarcinoma: 1.60, in lung metastasis: 1.47, in liver metastasis: 1.08)." (PMID 37686184, 2023).
lung carcinoma (1 paper, 2023). "Furthermore, CYP2C8 expression was also detected in many human lung cancer cell lines." (PMID 37686184, 2023).
renal dysfunction (1 paper, 2022). "In this study, we analysed the relationship between CYP2C8 gene polymorphism and renal dysfunction." (PMID 35135554, 2022). "In the clinic, patients with the CYP2C8 (rs1058932) AG genotype had a higher incidence of renal dysfunction than those with the AA and GG genotypes after taking HCQ." (PMID 35135554, 2022).
Wilson disease (1 paper, 2021). A very rare inherited multisystemic disease presenting non-specific neurological, hepatic, psychiatric or osseo-muscular manifestations due to excessive copper deposition in the body. "Gene expression of analyzed enzymes ranged between 18 and 65% compared to control group and significantly lower protein content of CYP1A1, CYP1A2, CYP2C8, CYP2C9, CYP3A4 and CYP3A5 enzymes was observed in Wilson’s disease." (PMID 34117631, 2021).
cancer (31 papers, 2009 to 2025). A tumor composed of atypical neoplastic, often pleomorphic cells that invade other tissues. "We speculate that CYP2C8 may mediate peroxisome-associated functions to stabilize the intracellular reactive oxygen species environment, thereby reducing the malignancy of cancer cells to a certain extent and leading to a better prognosis." (PMID 40108724, 2025). "Interestingly, CYP2C8 is included in their Cancer Gene Census, a list of genes which contain mutations causally implicated in cancer, with the level of evidence (Tier 2) described as “strong indications of a role in cancer, but with less extensive available evidence (than Tier 1)”." (PMID 32872162, 2020). "Then by univariate cox analysis, CYP2C8 was determined to be significantly associated with OS, DFI and PFI in a range of cancers, such as PAAD, KIRP, GBMLGG, etc.." (PMID 40108724, 2025). "Subsequently, KM curves were utilized to more visually demonstrate the prognostic potential of CYP2C8 in a number of cancer types with significant survival differences between high and low expression groups." (PMID 40108724, 2025). "In the future, we will focus on the identity of CYP2C8 in the metabolic microenvironment and immune microenrivronment of cancer cells and explore the specific mechanism by which it affects cancer progression." (PMID 40108724, 2025). "We searched a large number of literatures and found that few studies have investigated CYP2C8 as a tumor biomarker, so we attempted to perform a pan-cancer analysis of it." (PMID 40108724, 2025). "CYP2C8 is responsible for the metabolism of 5% of clinically prescribed drugs, including antimalarials, anti-cancer and anti-inflammatory drugs." (PMID 38650020, 2024). "Supported with the available in vitro data, our PBPK analysis suggested a significant induction of CYP2C8 expression during pregnancy based on the clinical PK data of paclitaxel in pregnant patients with cancer." (PMID 38140068, 2023). "Out of 31 analyzed cancers, seven show decreased expression of this enzyme, which shows that reduced expression of CYP2C8 is common in cancers." (PMID 36765904, 2023). "Tucatinib (CYP2C8 substrate) and quercetin (CYP2C8 inhibitor) are two common drugs for the treatment of cancer." (PMID 35289238, 2022). "This approach confirms the role of oncogenes recurrently involved in the onset and progression of CRC and contributes to the controversial role of CYP2C8 as an active driver of cancer." (PMID 29507673, 2018). "With this approach, known oncogenes recurrently involved in the onset and progression of CRC are confirmed, and a new candidate oncogene, whose role has been a matter of recent debate, CYP2C8, is proposed as an active driver of cancer." (PMID 29507673, 2018). "CYP2C8, 2C9, 2J2 and sEH expression has been detected in several tumor tissues and cells, which supports a role for EETs in cancer." (PMID 25406731, 2014). "Initially, we showed the pan-cancer expression landscape of CYP2C8." (PMID 40108724, 2025). "Finally, we comparatively verified the differential expression of CYP2C8 in some cancer types by immunohistochemical profiles derived from the HPA database." (PMID 40108724, 2025). "These include older age, presence of cancer and its type, type of bisphosphonate agent and duration of therapy, concomitant osteoporosis or osteopenia with cancer, diabetes, corticosteroid therapy, alcohol and chemotherapeutic agents, and gene polymorphisms including MMP2 and CYP2C8." (PMID 36157219, 2022). "However, recent studies have detected a sustained high level of EETs by upregulated CYP2C8, 2C9 and 2J2, or downregulated sEH in various cancers such as renal, lung, basal cell, bladder, ovarian, colon, and prostate cell carcinomas." (PMID 25406731, 2014). "In addition, there were significant metabolic pathway differences between the high and low expression groups of CYP2C8, which may also have an impact on cancer development." (PMID 40108724, 2025).
cancer (continued). "Some examples of anti-cancer drugs metabolized by CYP enzymes include tamoxifen by CYP2D6, docetaxel and cyclophosphamide by CYP3A4/5, and paclitaxel by CYP2C8." (PMID 41009411, 2025). "Of particular note was the finding that to recover the observed data in cancer patients with moderate RI (CrCL 20 to 39 mL/min), reductions of hepatic CYP3A4 and CYP2C8 expression, which reflect the effects of RI, had to be included in the simulations." (PMID 37514108, 2023). "A notable finding was that for recovery of the observed data in cancer patients with moderate RI (CrCL 20 to 39 mL/min), reductions of hepatic CYP3A4 and CYP2C8 abundances, which reflect the effects of RI, had to be included in the simulations." (PMID 37514108, 2023). "After assessing the diagnosis and prognostic values of identified key regulators in both the TCGA and GEO verification datasets, CXCL8, CYP2C8, and E2F1 were selected, which were reported as potential biomarkers in some cancers." (PMID 32851080, 2020). "The results indicated that some crucial cancer-related pathways were related to the high expression of CXCL8 and E2F1 and the low expression of CYP2C8, which was consistent with the expression level results and prognostic results." (PMID 32851080, 2020). "Conversely, CYP2C8 and CYP4A11 showed high expression and good prognosis, suggesting a potential protective role against cancer pathogenicity." (PMID 32851080, 2020). "In chemical carcinogenesis metabolism, benzo[a]pyrene can be metabolized by CYP2C8, CYP2C9, CYP2C18, and CYP2C19, and then finally transformed into the DNA adduct (+)‐trans‐BPDE‐N2‐dG, which has been shown to promote cancers of the skin, lung, and stomach." (PMID 29479826, 2018). "Across 5 cancer types, 109 patients who received paclitaxel exhibited activation of NR1I2, many with concurrent activation of CYP2C8 or CYP3A4 – known members of paclitaxel’s metabolic pathway." (PMID 29783934, 2018). "Some of them are cancer related, such as POU2F3, NKD1 and CYP2C8, while LINC00189, GCC2 and OR9Q1 genes are rarely reported in human diseases." (PMID 27602771, 2016). "Although many studies have focused on EET synthesis and metabolic enzymes in several cancers, the characteristics and roles of EET isoforms such as CYP2C8, 2C9, and 2J2, and sEH in BC remains poorly understood." (PMID 25406731, 2014). "However, FCN3, SLC22A1, ADH4, CYP2C8, SLC10A1, F9, and FBP1 were significantly downregulated in HCC tissue compared to the matched para-carcinoma tissue." (PMID 38664521, 2024). "Notably, several well-characterized cancer-related genes (e.g., ZKSCAN1, ABCB4 and CYP2C8) were found to generate circRNAs with significant changes in tumor samples." (PMID 31900416, 2020). "In addition, we identified CYP2C8 as a novel BLCA target and generalized it to pan-cancer." (PMID 40108724, 2025). "For CYP2C8, most studies reported minimum to no changes in patients with cancer." (PMID 38140068, 2023).